IL1B (interleukin 1 beta)
Diseases named in the same sentence as IL1B in open-access papers (continued):
Sharing a sentence is not in itself a finding about the gene and the disease.
depression (1,018 papers, 2009 to 2026). "Interleukin‐6 (IL‐6), tumor necrosis factor‐alpha (TNFα), and interleukin‐1 beta (IL‐1β) are three significant cytokines that have been widely investigated concerning the causes of major depressive disorder." (PMID 41479745, 2026). "One study reported that polymorphisms of rs1143627 AA and rs16944 GG genotypes of IL-1β in recurrent depression." (PMID 39841732, 2025). "IL-17 A-induced inflammatory mediators, including IL-6, IL-1β, Ptgs2, Csf2, and Cxcl1, can cause myocardial inflammation and depression [,14], and have been associated with endotoxin-induced cardiac dysfunction and shock [14,]." (PMID 41311862, 2025). "Increased levels of IL-1β have been linked to an increase in Hamilton depression rating scale (HAMD) scores." (PMID 40573262, 2025). "Although effect sizes were small, higher levels of TNF-α, IL-1β, IL-6, and IL-8 were all linked to either more depressive symptoms and/or greater odds of meeting criteria for clinical depression." (PMID 39902492, 2025). "Epileptic seizures can activate the HPA axis through inflammatory pathways involving interleukin-1β (IL-1β) and nuclear factor-kappa B (NF-κB), resulting in elevated cortisol levels and increased risk of depression." (PMID 40641625, 2025). "Individuals with depression often exhibit elevated levels of inflammatory markers including IL-1β, IL-6, TNF-α, and CRP, which are directly associated with acute cardiovascular events." (PMID 41179812, 2025). "Inflammation plays a significant role in the overlap between sickness behavior and depression, as both are associated with elevated levels of pro-inflammatory cytokines, such as IL-1B, IL-6, and TNF-alpha." (PMID 40282388, 2025). "Neuroinflammation is a significant pathogenic factor in depression, characterized by the excessive secretion of inflammatory cytokines like IL-1β in the brain." (PMID 40001468, 2025). "In contrast to IL-6, TNF-α and IL-1β levels were both associated with an increased odds of actually meeting criteria for clinical depression." (PMID 39902492, 2025). "For example, variations in the gene encoding for IL-1β have been linked to increased levels of this cytokine in individuals with depression, highlighting the role of genetic predisposition in modulating inflammatory responses." (PMID 40004109, 2025). "IL-1β is another pro-inflammatory cytokine that has been implicated in the development of depression and is one of the most studied cytokines." (PMID 40305200, 2025). "The purpose of this study was to examine associations between cytokines TNF-α, IL-1β, IL-6, and IL-8 and depression among a community-based sample of adolescents (13–19 years of age)." (PMID 39902492, 2025). "Interleukin-1β (IL-1β) levels were almost doubled in the depressed group (18.5 vs. 8.9 pg./mL, p < 0.001; d = +1.46), and were significantly associated with depression risk (OR = 1.05, 95% CI: 1.01–1.09)." (PMID 40823578, 2025). "Emerging studies further highlight a close association between the development and progression of depression and the involvement of key proinflammatory cytokines IL-1β, TNF-α, and IL-6." (PMID 40710585, 2025). "Although IL-1β is a proinflammatory cytokine and is considered to play a pivotal role in depression, increased inflammatory cytokines associated with depression is often derived from peripheral measure such as blood or CSF." (PMID 40179065, 2025). "A 2023 large-scale two-sample MR study analyzing 41 inflammation-related factors across over 130,000 depression cases found that only a few cytokines, such as IL-18, IL-1β, and RANTES, exhibited protective associations with depression risk." (PMID 41561993, 2025). "Its extracellular form acts as a pro-inflammatory cytokine that promotes the secretion of IL-6, TNF-α, and IL-1β, molecules that are closely linked to depressive disorder." (PMID 41375608, 2025). "The treatment response of depression is associated with specific genetic variants and methylation status of the gene IL-1β." (PMID 38459460, 2024).
depression (continued). "Both animal models and clinical studies demonstrate an increased inflammatory milieu associated with depression, including increased levels of interleukin-1beta (IL-1b), IL-6, tumor necrosis factor-alpha (TNFa), and interferon-gamma (IFN-g)." (PMID 39297528, 2024). "The NOD-like receptor thermal protein domain associated protein 3(NLRP3) inflammasome's involvement in the regulation of IL-1β secretion by microglial cells underscores its contribution to the inflammatory processes linked to depression." (PMID 38377025, 2024). "One study found that cytokines and tryptophan metabolites predicted depression during pregnancy and that IL-1β and IL-6 levels were associated with severity of depression symptoms during pregnancy and postpartum." (PMID 38820411, 2024). "Pro-inflammatory cytokines such as tumor necrosis factor-alpha (TNF-α), interleukin 6 (IL-6), and interleukin 1 beta (IL-1β) are elevated in psoriasis and have been implicated in the pathophysiology of depression and anxiety." (PMID 39335361, 2024). "Polymorphisms in IL1B play a significant role in depression, multiple inflammatory-associated disorders, and susceptibility to infection." (PMID 38858637, 2024). "Among the various cytokines implicated in the communication between immune cells of the peripheral system and the brain, TNF-α, IL-1β, IL-18, and IL-6 have been identified as crucial players, with elevated levels of these mediators associated with depression." (PMID 38916735, 2024). "The primary cytokines linked to depression consist of various indicators like Tumor Necrosis Factor α (TNFα), Interleukin (IL)-1β, IL-18, and Interferon (INF)-γ." (PMID 38731995, 2024). "Plasma IL-1β levels are significantly associated with depression and depressive severity, and also related to treatment-refractory depression." (PMID 38459460, 2024). "The XJ strain’s significant induction of IL-1β and IL-6 in the brain implies a propensity for causing severe neurological damage, aligning with observed clinical symptoms like muscle spasms and depression." (PMID 39170631, 2024). "There is growing evidence that abnormal neuroinflammatory responses such as higher concentrations of pro-inflammatory cytokines such as TNFα and IL-1β in the brain promote susceptibility to psychiatric conditions like depression." (PMID 39682736, 2024). "IL-1β is a pivotal inflammatory mediator implicated in diabetes mellitus and depression, associated with compromised insulin secretion and various depressive symptom mechanisms." (PMID 38916735, 2024). "Upon activation, microglial cells release inflammatory cytokines, such as IL‐6, TNF‐α, and IL‐1β, which are associated with the neuronal degeneration often observed in depression." (PMID 39554370, 2024). "Peripheral levels of inflammatory cytokines are elevated in people with MDD, and the inflammasome pathway, which leads to IL1β activation, has been implicated both in depression and HIV-associated neurological dysfunction." (PMID 39175522, 2024). "The NLRP3 inflammasome processes pro-IL-1β into mature interleukins and act as a pro-inflammatory mediator, it has been confirmed that IL-1β was elevated in the serum of depression patients and associated with depression inventory scores." (PMID 36859349, 2023). "It was shown that depression in acute coronary syndrome was significantly associated with the level of IL-1β and −511T allele." (PMID 37510364, 2023). "In another study, spared nerve injury (SNI)-induced depression was associated with the activation of microglia through the upregulation of Iba1 and CD11b and increased levels of pro-inflammatory mediators (IL-1β, TNF-α, and CD68) in the PFC54." (PMID 36747075, 2023). "Nuclear factor I-A (NFIA) has been identified as the direct target for miR-212 which in turn regulates the level of the inflammatory factors TNF-α, IL-1β, and IL-6, which are generally associated with depression in human studies." (PMID 40655973, 2023).
depression (continued). "It was also found that rs16944 and 1143623 of the IL1B gene were associated with both depression and BD." (PMID 37510364, 2023). "For example, the IL6-174G/C polymorphism in interaction with various stress factors increases the risk of depression, and the IL1B-511C/T was associated with more severe depression following chronic interpersonal stress exposure." (PMID 37510364, 2023). "Most importantly from our studies, the production of IL-1β was associated more often with advanced breast cancer, as well as a higher level of depression, evidenced by two different clinical trials, respectively." (PMID 37181043, 2023). "For example, rs16944 IL1B showed a significant association with depression in scientific studies, symptom severity, as well as with SCZ and BD." (PMID 37510364, 2023). "Several studies have reported that caspase 1, IL-1β, and IL-18 are associated with depression, anxiety, and fatigue, indicating the implication of the NLRP3 inflammasome in the pathophysiology of these diseases." (PMID 36675440, 2023). "There are many studies that show depression is associated with increased brain or peripheral IL-1b production, as well as HPA axis hyperactivity." (PMID 36909194, 2023). "Il-1β causes fluoxetine resistance in the animal model of epilepsy-induced depression, with subsequent presynaptic 5-HT1A receptor up-regulation." (PMID 36838809, 2023). "Loss of TET2 activated the NLRP3/IL-1β pathway of microglia in AR mice, further accelerating the anxiety and depression-like behaviors." (PMID 38012545, 2023). "Several studies have reported that inflammation in the brain and the associated over-release of pro-inflammatory cytokines TNF-α, IL-6, or IL-1β can lead to a loss of hippocampal neurogenesis, promoting depression-like behaviors." (PMID 37238920, 2023). "For example, numerous studies have revealed a relationship between the minor C allele, or CC genotype, of IL1B-511C/T and clinical psychopathological symptoms of different forms of depression." (PMID 37510364, 2023). "On the other hand, depression is associated with high levels of IL-1β, possibly responsible for activating a common pathway leading to depression and cognitive decline." (PMID 38138916, 2023). "For example, increased tumor necrosis factor-α (TNF‐α) and interleukin (IL)‐1β, IL-6, and IL-17A are linked to the occurrence of anxiety and depression in coronary heart disease patients." (PMID 37878890, 2023). "Recently, it has been shown that IL-1β is associated with depression but the magnitude of this association and its relationship with other involved factors in depression needs more clarification." (PMID 36368945, 2022). "Both CRP and IL-1β have been implicated in the pathophysiology of psychological conditions, particularly major depressive disorders." (PMID 36612568, 2022). "Cytokines, such as IL6, TNFα, and IL1β, are not only involved in the pathogenic mechanism of depression, but also of pain and fatigue." (PMID 36422176, 2022). "An inflammation-dependent decline in adult neurogenesis observed in depression is mainly linked to microglia-released cytokines such as IL-1β, IL-6, TNF-α, and INF-α." (PMID 35455082, 2022). "Higher concentrations of IL-1β were associated with lower whole-brain fractional anisotropy, particularly in people with depression (ρ = − 0.67; p < 0.001)." (PMID 36261698, 2022). "Evidence suggests a strong association between depression, anxiety, cachexia, and high levels of cytokines expression (IL-1β, IL-6, IL-10, TNF-α, INF-γ, and fractalkine [CX3X]) in cancer patients." (PMID 36067147, 2022). "Blockade or deletion of D3 caused activation of those glia, with symptoms of depression and increased levels of IL-1β, IL-6, and TNF in dopaminergic neurons." (PMID 36507331, 2022). "‘T’ allele of rs1143627 IL1B SNP was associated with higher level of depression (ZDS was 40.6±8.7, 39.2±7.3 and 38.3±8.0 in case of ‘T/T’, ‘T/C’ and ‘C/C’ genotypes, respectively, p-value=0.025 in log additive model)." (PMID 35964023, 2022).
depression (continued). "This study clearly demonstrated an association between peripherally measured IL-1β and white matter integrity in depression as assessed by DTI." (PMID 36261698, 2022). "Other IL1B variant (rs1143627) was associated with patient reported global treatment outcome, while majority of the studied IL1B variants were related to the preoperative level of depression." (PMID 35964023, 2022). "In our study, some IL1B variants were significantly associated with the preoperative level of depression." (PMID 35964023, 2022). "The results suggest that microstructural changes in the corpus callosum are associated with increased peripheral IL-1β concentrations in depression." (PMID 36261698, 2022). "We chose IL-1β because it has previously been associated with depression yet exhibited several values in our current assays that were out of range low." (PMID 35332134, 2022). "The main result of this study showed an altered association of IL-1β with fractional anisotropy, as can be measured using diffusion tensor imaging, in depression." (PMID 36261698, 2022). "Among the cytokines believed to be implicated in the association between stress and depression are IL-1β and IL-6, known to be potent activators of the HPA axis, which, consequently, can modulate noradrenergic and serotonergic mechanisms." (PMID 36185078, 2022). "Depression exhibited increases in IL-1β and IL-18 levels associated with activation of NLRP3 inflammasome." (PMID 35069768, 2022). "Consistently, another study in depression model mice found that rTMS reversed the down-regulation of astrocytes and inhibited high levels of IL-6, and IL-1β caused by chronic unpredictable mild stress (CUMS) in the hippocampus and prefrontal cortex." (PMID 36188478, 2022). "LPS induces pro-inflammatory factors in the immune cells of animals, such as TNF-α, IL-1β, and interleukin-6 (IL-6), which in turn cause depression-like behaviors." (PMID 35165207, 2022). "IL1B rs16944 ‘G’ allele carriers also showed higher level of depression (ZDS was 40.6±8.8, 39.2±7.3 and 38.0±8.0 in case of ‘G/G’, ‘A/G’ and ‘A/A’ genotypes, respectively, p-value=0.025 in log additive model)." (PMID 35964023, 2022). "TNF-α and IL-1β are associated with neuronal plasticity, which is further linked with the cognitive abilities of patients with depression and brain innate immunity." (PMID 36014820, 2022). "A single dose of ketamine reduced elevatory serum levels IL-1β and IL-6 to normal in depression-like rats caused by neuralgia." (PMID 34079622, 2021). "The “usual suspects” associated with depression tend to be elevated interleukins (ILs), interferons (IFNs) and acute phase proteins, including IL-1β, IL-6, IL-2, IFN-γ, tumour necrosis factor alpha (TNF-α) and C-reactive protein (CRP)." (PMID 34816138, 2021). "Stress is a major environmental etiological factor in mood disorders, and P2RX7 activation has been associated with an inflammatory and stress-mediated depression-like phenotype with enhanced IL-1β release contributing to stress-induced depression." (PMID 34111150, 2021). "The NLRP3 inflammasome activation mediated IL-1β release and neuroinflammation has recently been implicated with great gusto in major depressive disorder (MDD) pathogenesis." (PMID 34443594, 2021). "Elevated levels of IL-1β in subjects with childhood maltreatment and other stressors are closely associated with depression-like behavior in brain tissue and serum." (PMID 34526897, 2021). "Higher levels of IL-1β were associated with more severe symptoms of withdrawal/depression and thought problems." (PMID 32495042, 2021). "Our findings that change in sleep time was inversely associated with anxiety, depression, and serum cytokine levels (IL-2, IL-1β, IL-6, TNFα) are in keeping with the consensus of these reviews." (PMID 33598780, 2021).
depression (continued). "For example, LPS administration at 30 days post-TBI exacerbated cognitive impairment and induced depression-like behavior, both of which were associated with microglial reactivation and an exaggerated production of pro-inflammatory cytokines IL1-β and TNFα." (PMID 34944762, 2021). "Clinical studies reveal that depression is associated with elevated levels of IL-6 and IL-1β proteins in the cerebrospinal fluid." (PMID 34576218, 2021). "Studies suggest that depression is associated with elevated levels of both pro-inflammatory and anti-inflammatory cytokines, e.g., IL-1β, IL-6, IFN-γ, TNF-α, and C-reactive protein (CRP)." (PMID 33920992, 2021). "Currently, known cytokines associated with depression are IL-1β, IL-6, TNF-α, IFN-γ, c-reactive protein (Müller, 2014)." (PMID 34526897, 2021). "As one of the proinflammatory cytokines, IL-1β is implicated in stress, depression, and central nervous system (CNS) dysregulation." (PMID 32328132, 2020). "Previous studies found higher risk of depression in IL-1β gene rs16944 carriers of the higher synthesizing A allele, in schizophrenia and Alzheimer disease patients." (PMID 32377159, 2020). "In humans, IL-1β polymorphisms are linked to the levels of related cytokine expression and consequently to elevated risk of depression in different populations." (PMID 32377159, 2020). "IL-1β knockdown significantly attenuated the memory deficits and anxiety- and depression-like behaviors caused by LPS." (PMID 32983956, 2020). "Some studies suggested a role of IL-1β in reducing BDNF in patients with depression, indicating that an increase in IL-1β concentrations was associated with a decrease in BDNF concentrations." (PMID 32517269, 2020). "Excessive expression of interleukin (IL)-1β in the brain causes depression and cognitive dysfunction." (PMID 33182607, 2020). "Cytokines released by cell-mediated immunity, like IL-6, TNF-alpha, IL-1b, play a role in disorders like depression where these cytokines can act as risk factors or aggravate the state of depression." (PMID 33240722, 2020). "Enhanced IL-1β production in astrocytes is associated with the pathogenesis of major depressive disorder." (PMID 32611425, 2020). "Incident depression was significantly associated with increases in IL-1β, IL-6, and IL-8 serum levels in late-life depression." (PMID 32858844, 2020). "The presence of the allele A of rs16944 increases the IL-1β production, and it was associated with elevated risk of depression in schizophrenic spectrum disorders, depressive symptoms in Alzheimer disease, and depressed state in breast cancer patients." (PMID 32377159, 2020). "Sum scores of the Beck’s depression inventory were associated with higher levels of inflammatory markers interleukin-1beta (IL-1β), tumor necrosis factor-alpha (TNF-α), and interleukin-8 (IL-8), after LPS induction in whole blood." (PMID 32669537, 2020). "Pro-inflammatory cytokine IL-1β was found to be linked to neuronal plasticity, which was required for cognitive ability in patients with depression." (PMID 30658416, 2019). "Inflammatory factors were reported to be associated with depression; as such, we tested the expression of IL-1β and IL-6 in serum samples of 30 normal donors (ND), 30 GC patients, and 30 GC patients with depression." (PMID 31396300, 2019). "Direct injection of inflammatory cytokines, such as TNF-α and IL-1β, into the brain of animals can produce depression-like behaviors, such as loss of pleasure, decreased activity, and decreased food intake." (PMID 31141940, 2019). "We therefore examined Il1b and Bdnf gene expressions that have been implicated as biomarkers for depression." (PMID 30042304, 2018). "The degree of depression was associated with the levels of IL-1β, TNF-α, and IL-8, while the degree of comorbidity between depression and anxiety was associated with the IL-8 level." (PMID 29856741, 2018).